SCRN2 (secernin 2)
Synonyms: Ses2
Tractability: PROTAC: ubiquitination databases record sites on it; its protein half-life has been measured.
Gene: Protein-coding gene on chromosome 17 (47,837,683 to 47,842,125, reverse strand). Ensembl gene ENSG00000141295.
Subcellular location (Human Protein Atlas): Nucleoplasm; Golgi apparatus
Gene Ontology:
Molecular function: protein binding; cysteine-type exopeptidase activity; dipeptidase activity
Biological process: proteolysis
Cellular component: extracellular exosome; nucleoplasm
Genetic constraint (gnomAD): Loss-of-function variants: 33 observed, 44 expected, observed/expected ratio (o/e) 0.75, 90% interval 0.57 to 1. The upper end of that interval is the gene's LOEUF score, 1, which puts it in group 4 of 6, group 1 being the genes least tolerant of losing a copy. Missense variants: 526 observed, 569.41 expected, observed/expected ratio (o/e) 0.92, 90% interval 0.86 to 0.99. Synonymous variants: 240 observed, 233.91 expected, observed/expected ratio (o/e) 1.03, 90% interval 0.92 to 1.14.
Homologues: Orthologues: chimpanzee SCRN2 (99% identical), macaque MRPL10 (96% identical), dog SCRN2 (89% identical), rabbit SCRN2 (88% identical), mouse Scrn2 (86% identical), rat Scrn2 (85% identical), guinea pig SCRN2 (84% identical), pig SCRN2 (81% identical), tropical clawed frog scrn2 (64% identical), zebrafish scrn2 (62% identical), Drosophila melanogaster CG10098 (22% identical). Paralogues in human: SCRN3 (52% identical), SCRN1 (50% identical).
Diseases named in the same sentence as SCRN2 in open-access papers:
SCRN2 is named in the same sentence as 8 diseases in open-access papers, as found by Europe PMC text mining. Sharing a sentence is not in itself a finding about the gene and the disease. The quoted sentences say what the papers report.
breast carcinoma (1 paper, 2025). "Results showed that SCRN2 promoter generally possessed low DNA methylation levels in most breast cancer cell lines, including TNBC cells." (PMID 39836524, 2025). "In addition, the frequency of copy number deletion of SCRN2 in all breast cancers and TNBC was ≈ 0.5% and 0%, respectively." (PMID 39836524, 2025).
cancer (2 papers, 2021 to 2025). A tumor composed of atypical neoplastic, often pleomorphic cells that invade other tissues. "This study defines SCRN2 as a novel tumor suppressor in TNBC to suppress cancer progression and enhance PARP inhibitor sensitivity through stabilizing KMT2C and reveals SCRN2 as a potential biomarker and therapeutic target for TNBC." (PMID 39836524, 2025). "In this study, we provide the first evidence that SCRN2 functions as a novel tumor suppressor in TNBC to block cancer progression and enhance therapeutic response to PARP inhibition." (PMID 39836524, 2025). "Notably, SCRN2 was downregulated in several types of cancer in the CPTAC dataset, indicating that our findings are not limited to TNBC." (PMID 39836524, 2025). "It is reasonable to speculate that SCRN2 may also act as a tumor suppressor in other types of cancers, which should be explored in the near future." (PMID 39836524, 2025). "Of note, the roles of other 11 screened proteins in cancer progression have been documented previously, while the functional and mechanistic role of SCRN2 in human cancer remains unknown, Thus, we chose the poorly characterized SCRN2 for further investigation." (PMID 39836524, 2025). "Herein, we first report that secernin 2 (SCRN2), an uncharacterized gene in human cancer, acts as a novel tumor suppressor in TNBC to inhibit cancer progression and enhance therapeutic sensitivity to poly(ADP‐ribose) polymerase (PARP) inhibition both in vitro and in vivo." (PMID 39836524, 2025).
tumor (1 paper, 2025). "CCK8 and colony formation assays showed that knockdown of KMT2C partially rescued the decreased proliferative potential, colony formation capacity, and xenograft tumor growth in mice caused by SCRN2 overexpression." (PMID 39836524, 2025). "Third, we discovered that SCRN2 exerts its tumor‐suppressive functions by stabilizing the putative tumor suppressor KMT2C." (PMID 39836524, 2025). "The suppressive effects of Olaparib on tumor growth were more pronounced in mice bearing SCRN2‐overexpressing tumors than in those bearing tumors expressing the empty vector." (PMID 39836524, 2025). "Together, these findings verify the tumor suppressor role of SCRN2 in TNBC and identify SCRN2 as a potential therapeutic target for TNBC." (PMID 39836524, 2025). "Taken together, these results suggest that SCRN2 acts as a tumor suppressor in TNBC." (PMID 39836524, 2025). "A series of in vitro and in vivo functional assays with overexpression or knockdown of SCRN2 demonstrated that SCRN2 inhibited TNBC cell proliferation, migration and invasion in vitro, and impeded xenograft tumor growth and lung metastasis in mice." (PMID 39836524, 2025). "In conclusion, the findings presented here revealed the functions of SCRN2 as a novel tumor suppressor in TNBC and highlighted its potential implication of SCRN2 as a therapeutic target for TNBC." (PMID 39836524, 2025).
SCRN2 also shares sentences with these, for which no sentence is quoted: Alzheimer disease (1 paper); autism (1); Cognitive impairment (1); lung carcinoma (1); neurodegenerative disease (1).